HPRT1 (hypoxanthine phosphoribosyltransferase 1)
Diseases named in the same sentence as HPRT1 in open-access papers (continued):
Sharing a sentence is not in itself a finding about the gene and the disease.
Huntington disease (4 papers, 2009 to 2024). Huntington disease (HD) is a rare neurodegenerative disorder of the central nervous system characterized by unwanted choreatic movements, behavioral and psychiatric disturbances and dementia. "Our findings imply that many DETs (including App, Hprt1 and Sncb) associated with both Huntington's disease and schizophrenia are also involved in neuronal/cell death processes." (PMID 19799774, 2009). "We confirmed the association of endogenous UBL3 with the RNA-binding proteins FUS and HPRT1—both listed in the Neurodegenerative Diseases Variation Database (NDDVD)—and with LYPLA1, which is involved in Huntington’s disease, using immunoprecipitation (IP)-western blotting analysis." (PMID 39148092, 2024).
Parkinson disease (4 papers, 2011 to 2020). A progressive degenerative disorder of the central nervous system characterized by loss of dopamine producing neurons in the substantia nigra and the presence of Lewy bodies in the substantia nigra and locus coeruleus. "Genes showing similar co-expression patterns have been previously linked to Alzheimer’s (ANK1) and Parkinson’s disease (UBE2E2, PCMT1, HPRT1 and RIT2)." (PMID 25493648, 2014).
Purine metabolic disorders (4 papers, 2020 to 2025). "As a rate-limiting enzyme in the purine salvage pathway, the downregulation of HPRT1 can impair this pathway, leading to purine metabolic disorders and increased uric acid production." (PMID 40508129, 2025).
renal failure (4 papers, 2017 to 2024). "It has also been reported that pathogenic variants in the HPRT1 gene lead to renal calcinosis and renal insufficiency." (PMID 35559039, 2022).
acute lymphoblastic leukemia (3 papers, 2013 to 2023). Leukemia with an acute onset, characterized by the presence of lymphoblasts in the bone marrow and the peripheral blood. "The thiopurine drug 6-mercaptopurine (6-MP), which has been used for acute lymphoblastic leukemia (ALL) and chronic myeloid leukemia (CML) treatment, competes with HPRT1 substrates and thereby inhibits HPRT1 activity." (PMID 37737247, 2023).
bladder cancer (3 papers, 2016 to 2019). "We therefore downloaded RSEM-normalized RNA-seq values for A3A, A3B, and HPRT1 from 410 bladder cancers (BLCA), 197 cervical cancers (CESC), and 549 head and neck cancers (HNSC) from the TCGA." (PMID 31841499, 2019). "Studies in bladder cancer cells under hypoxia showed that β2-MG and Hypoxanthine phosphoribosyltransferase-1 (HPRT) were the most suitable reference genes for normalizing gene expression." (PMID 28970964, 2017).
colorectal tumor (3 papers, 2010 to 2020). "The absolute quantification of SerpinB3, COX-2 and β-Catenin mRNA expression, normalized by the HPRT1 housekeeping gene, was assessed in 105 primary human colorectal tumors (T) and in their corresponding adjacent non-tumor mucosa (N) by quantitative Real-Time PCR." (PMID 28178650, 2017).
developmental delay (3 papers, 2023 to 2025). "Consequently, all infants with developmental delay and high uric acid levels should have prompt HPRT1 gene mutation analysis to minimize the time to diagnosis." (PMID 38653184, 2024).
endometrial cancer (3 papers, 2014 to 2021). Primary or metastatic malignant neoplasm involving the endometrium (mucous membrane that lines the endometrial cavity). "Besides, others have demonstrated that the increased expression of HPRT1 in endometrial cancer samples was correlated with the survival outcomes of patients." (PMID 34231338, 2021). "We have determined that there is a significant elevation of JAG2, HPRT1, AURKA, and PGK1 expression in endometrial cancer." (PMID 30679932, 2019). "Thus, according to the statistical analysis performed on the expression level of the 10 selected reference genes, GUSB, HPRT1 and PPIA were the best candidate for normalization purposes in gene expression studies in endometrial cancer versus normal tissue." (PMID 25473950, 2014).
epilepsy (3 papers, 2009 to 2024). A brain disorder characterized by episodes of abnormally increased neuronal discharge resulting in transient episodes of sensory or motor neurological dysfunction, or psychic dysfunction. "Using ddPCR, we then validated overexpression of HML-2 RNA in malignant glioma samples compared with nontumoral epilepsy tissues (HML-2/HPRT1 ratio)." (PMID 37395282, 2023).
ischemia (3 papers, 2018 to 2023). A hypoperfusion of the BLOOD through an organ or tissue caused by a PATHOLOGIC CONSTRICTION or obstruction of its BLOOD VESSELS, or an absence of BLOOD CIRCULATION. "Our results showed that Hmbs and Hprt1 were the most stable genes in the ischemia-vulnerable CA1 and ischemia-resistant CA2-3,DG sectors, respectively." (PMID 36769080, 2023).
viral infection (3 papers, 2017 to 2024). "Many studies have reported that experimental conditions, such as dietary restriction, metals, viral infection, and herbicides, influence the expression of reference genes that have traditionally been considered as reference genes (e.g., GAPDH, HPRT1, and 18S rRNA)." (PMID 37780581, 2023).
amyotrophic lateral sclerosis (2 papers, 2020 to 2022). Amyotrophic lateral sclerosis (ALS) is a neurodegenerative disease characterized by progressive muscular paralysis reflecting degeneration of motor neurons in the primary motor cortex, corticospinal tracts, brainstem and spinal cord. "HPRT1 encodes hypoxanthine phosphoribosyltransferase 1, and mutated HPRT1 affects amyloid precursor protein (APP) gene expression in AD and amyotrophic lateral sclerosis (ALS)." (PMID 32461378, 2020).
Arthritis (2 papers, 2022 to 2023). Inflammation of a joint. "In a past study, HPRT1, B2M, and RPL13A were the stable genes in the arthritic joints of the KbxN serum transfer arthritis model, and the mRNA expression level of GAPDH significantly decreased with an increase in joint inflammation." (PMID 37894839, 2023).
brain tumors (2 papers, 2018 to 2023). "Depletion of HPRT1 reduced tumor growth and substantially sensitized the brain tumors to TMZ treatment." (PMID 37737247, 2023). "HPRT1 depletion or 6-MP treatment sensitizes brain tumors to TMZ treatment." (PMID 37737247, 2023). "RRM1 T52A expression, genetic interruption of HPRT1-mediated AICAR production, or administration of 6-mercaptopurine (6-MP), a clinically approved inhibitor of HPRT1, blocks TMZ-induced AMPK activation and sensitizes brain tumor cells to TMZ treatment in mice." (PMID 37737247, 2023). "HPRT1 depletion inhibited TMZ treatment-induced AMPK activation in brain tumor tissues and enhanced TMZ-induced γ-H2AX levels and apoptosis." (PMID 37737247, 2023). "Together, these results strongly suggested that HPRT1-mediated AMPK activation and subsequent RNR activation are instrumental for brain tumor chemoresistance to TMZ treatment." (PMID 37737247, 2023). "To determine the role of HPRT1 in brain tumor resistance to TMZ treatment in animals, we intracranially injected nude mice with luciferase-expressing MES28 or U87 cells with or without HPRT1 depletion." (PMID 37737247, 2023). "In each individual experiment using individual housekeeping genes, CNS-NB samples showed significantly elevated PLK4 expression levels when compared to non-embryonal brain tumors (LGG) (GAPDH p = 0.0016; HPRT1 p < 0.0001; HMBS p = 0.0116)." (PMID 30400339, 2018).
chronic obstructive pulmonary disease (2 papers, 2011 to 2015). A chronic and progressive lung disorder characterized by the loss of elasticity of the bronchial tree and the air sacs, destruction of the air sacs wall, thickening of the bronchial wall, and mucous accumulation in the bronchial tree. "With lipopolysaccharide stimulation, the expression level of hypoxanthine phosphoribosyltransferase 1 (HPRT1) and tubulin, beta (TUBB) increased in alveolar macrophages from chronic obstructive pulmonary disease patients." (PMID 25881111, 2015).
COVID-19 (2 papers, 2021 to 2022). A disease caused by infection with severe acute respiratory syndrome coronavirus 2. "A refined linear regression analysis of the proteomic hits (FDR < 0.05) further identified 23 upregulated proteins, of which the top 9 are the same and revealed 2 downregulated proteins in COVID-19+ patient urine, hypoxanthine phosphoribosyltransferase 1 (HPRT1) and CD5 molecule–like (CD5L)." (PMID 34767537, 2021).
esophageal cancer (2 papers, 2024). A primary or metastatic malignant neoplasm involving the esophagus. "Remarkably, in esophageal cancer, the risk of mortality was significantly elevated in the group with high HPRT1 expression compared to the group with low expression (HRs = 2.215, 95% CI: 1.143–4.293, p = 0.018)." (PMID 38485739, 2024). "The Kaplan-Meier survival curves highlighted that the OS of the HPRT1 high-expression group in esophageal cancer was shorter than that of the HPRT1 low-expression group (log-rank test, p = 0.016)." (PMID 38485739, 2024).
head and neck cancer (2 papers, 2017 to 2019). A primary or metastatic malignant neoplasm affecting the head and neck. "However, the minimum and maximum (min-max) range for head and neck cancer cell line SCC6 was calculated to be 0.490 for HPRT1 and 2.990 for ACTB while for SCC-1483 it was 0.409 for B2M and 4.093 for ACTB respectively." (PMID 28262749, 2017). "While in both non-small lung cancer cell lines - A549 and NCI-H226, GUSB was the least variable gene; for the head and neck cancer cell lines - SCC6 and SC1483, HPRT1 and PP1A, respectively showed the smallest variation." (PMID 28262749, 2017).
hepatic cancer (2 papers, 2021 to 2024). "In hepatic cancer cell lines, the first six stable reference genes were YWHAZ, ACTB, B2M, UBC, HPRT1, and RNA18S." (PMID 34752497, 2021). "In hepatic cancer cell lines, B2M, GAPDH, UBC, and HPRT1 were the first four stable nominees, respectively, and RNA18S was determined as the least stable ones." (PMID 34752497, 2021). "Moreover, in hepatic cancer cell lines including Huh7, HepG2, and PLC-PRF5, ACTB, HPRT1, UBC, B2M, and YWHAZ were among the first six stable genes ranked by geNorm, NormFinder, and RefFinder algorithm." (PMID 34752497, 2021). "Similarly, a panel of five reference genes, namely ACTB, HPRT1, UBC, YWHAZ, and B2M is also recommended for RT-qPCR data normalization of three hepatic cancer cell lines, including Huh7, HepG2, and PLC-PRF5." (PMID 34752497, 2021). "Besides that, a panel of five nominees, including ACTB, HPRT1, UBC, YWHAZ, and B2M showed higher stability than others in hepatic cancer cell lines." (PMID 34752497, 2021).
laryngeal carcinoma (2 papers, 2015 to 2016). Carcinoma that arises from the laryngeal epithelium. "In the tissue group, PPIA and RPL29 had the lowest M-values, followed by HPRT1, which suggests that these same genes are the most stable internal reference genes for the study of human laryngeal cancer tissues." (PMID 27957397, 2016). "According to the results of geNorm, in the cell line + tissue group, RPL29 and HPRT1 had the lowest M-values, followed by PPIA, suggesting that these are the most stable internal reference genes for the study of human laryngeal cancer cell lines and tissues." (PMID 27957397, 2016). "The mRNA expression of genes coding O-GlcNAc-cycling enzymes in laryngeal cancer tissue (SCLC) and non-cancerous laryngeal mucosa (NCLM) was estimated by real-time quantitative PCR analysis with the HPRT1 gene applied as a reference." (PMID 25315705, 2015).
lung squamous cell carcinoma (2 papers, 2020 to 2022). "We observed elevated levels of HPRT1 RNA to be indicative of poor overall survival in all the cancers above except for lung squamous cell carcinoma." (PMID 32532008, 2020).
mesothelioma (2 papers, 2024). A usually malignant and aggressive neoplasm of the mesothelium which is often associated with exposure to asbestos. "Mesothelin gene expression levels in major organ tissues (n = 24) and mesothelioma tissues (n = 4) were analyzed via qPCR relative to the housekeeping gene HPRT-1 to characterize mesothelin’s tissue distribution and assess its expression in canine mesotheliomas." (PMID 39315086, 2024).
osteoporosis (2 papers, 2020 to 2024). A condition of reduced bone mass, with decreased cortical thickness and a decrease in the number and size of the trabeculae of cancellous bone (but normal chemical composition), resulting in increased fracture incidence. "Our research group will explore the key role and regulatory network of HPRT1 in the pathogenesis of osteoporosis in subsequent studies by constructing HPRT1 knockout mice and primary osteoblast HPRT1 silencing models." (PMID 39500875, 2024). "On the basis of this gene function, HPRT1 is a promising intervention target for the regulation of purine metabolism to treat osteoporosis." (PMID 39500875, 2024).
pancreatic adenocarcinoma (2 papers, 2022 to 2024). "HPRT1 showed a positive correlation with stromal scores in GBM but a negative correlation in ACC, BRCA, LUSC, pancreatic adenocarcinoma (PAAD), STAD, and thymoma (THYM)." (PMID 38159260, 2024).
stomach cancer (2 papers, 2010 to 2015). "For example, the most unstable gene, HPRT1, in 'stomach cancer cell lines' has much wider range of expression compared to GAPDH or B2M." (PMID 20507635, 2010). "For 'stomach cancer cell lines,' the higher V4/5 (0.018) and V5/6 (0.028) values than V2/3 or V3/4 explain why the high-scoring HPRT1 and ACTB genes should be excluded." (PMID 20507635, 2010). "ACTB and GAPDH showed most abundant expression in both 'stomach cancer cell lines' and 'non-stomach cancer cell lines', but in contrast HPRT1 showed lowest expression level." (PMID 20507635, 2010).
thyroid tumor (2 papers, 2019 to 2020). A benign or malignant neoplasm affecting the thyroid gland. "They declared consistency between the different algorithms of NormFinder, BestKeeper, and GeNorm because all three suggested GUSB and HPRT1 as the most stably expressed genes in all thyroid tumours." (PMID 33110161, 2020). "The three algorithms were in agreement in identifying GUSB and HPRT1 as the most stably expressed genes in all thyroid tumors investigated." (PMID 31645594, 2019).
triple-negative breast carcinoma (2 papers, 2020 to 2024). An invasive breast carcinoma which is negative for expression of estrogen receptor (ER), progesterone receptor (PR), and human epidermal growth factor receptor 2 (HER2). "Further, overall survival analysis based on HPRT1 protein expression in triple-negative breast cancer patients suggested its association with clinical outcome." (PMID 32532008, 2020).
acute pancreatitis (1 paper, 2016). An acute inflammatory process that leads to necrosis of the pancreatic parenchyma. "The mRNA expression of B2M and HPRT1 in pancreatic tissues remained constant between the control group and MAP group, which indicated that B2M and HPRT1 are appropriate reference genes for caerulein-induced acute pancreatitis." (PMID 27069927, 2016). "In studies of caerulein-induced murine acute pancreatitis, ACTB, GAPDH, 18sRNA, beta-2 microglobulin (B2M), and hypoxanthine phosphoribosyltransferase 1 (HPRT1) have been frequently used as reference genes for comparison of mRNA transcription in pancreatic tissue." (PMID 27069927, 2016).
Anxiety (1 paper, 2023). Intense feelings of nervousness, tension, or panic often arise in response to interpersonal stresses. "In our gene-based analyses, HPRT1 was associated with anxiety, irritability and neuroticism." (PMID 37937232, 2023). "In particular, HPRT1 was associated with the only three phenotypes in which it could be tested: anxiety (p = 4.34E-04), irritability (p = 2.05E-06) and neuroticisim (p = 5.70E-08), since this gene is located in the X chromosome." (PMID 37937232, 2023).
bacterial meningitis (1 paper, 2013). Inflammation of the membranes surrounding the brain and spinal cord due to a bacterial infection. "We selected IL-1 beta, IL-6 and TNF alpha for the quantitative reverse transcriptase PCR, since they are known to be the major inflammatory cytokines detected in the CSF during bacterial meningitis, as control the house keeping genes GAPDH and HPRT1 were used." (PMID 23874613, 2013).
cholesteatoma (1 paper, 2020). A pathologic process characterized by the proliferation of keratinizing squamous epithelium resulting in the accumulation of keratin and cells in the middle ear and/or mastoid. "However, the differences in expression levels between tissue groups for each gene were small; only the expression of HPRT1, PGK1, PPIA, ATP5B and YWHAZ was significantly higher in healthy MA compared to the mucosa from the middle ear in cholesteatoma patients." (PMID 32915926, 2020).
cutaneous skin melanoma (1 paper, 2024). "In HNSC, KIRP, MESO, PRAD, cutaneous skin melanoma (SKCM), UCEC, and UCS, HPRT1 expression was associated with the OS of patients." (PMID 38159260, 2024).
disc degeneration (1 paper, 2011). "We analyzed matrix metalloproteinase-3 (MMP-3) expression which plays a major role in the disc degeneration process using Actb and combination of Hprt1 and CycA." (PMID 21615931, 2011).
endometrial tumors (1 paper, 2014). "In that investigation 38 endometrial tumors and associated normal specimens were examined using qPCR, followed by GeNorm and NormFinder algorithms, that found HPRT1, POLR2A and PPIA as the most stable reference genes." (PMID 25473950, 2014).
enteritis (1 paper, 2011). Inflammation of the small intestine. "RPL4, HPRT1 and B2M are reported as stably expressed and suitable candidate genes in intestinal tissues collected from healthy pig and from pigs with enteritis." (PMID 22023805, 2011).
Fanconi anemia (1 paper, 2021). Fanconi anemia (FA) is a hereditary DNA repair disorder characterized by progressive pancytopenia with bone marrow failure, variable congenital malformations and predisposition to develop hematological or solid tumors.
generalized dystonia (1 paper, 2023). "This novel HPRT1-variant can now be classified as pathogenic and severe because of the neonatal onset of generalized dystonia and the emergence of self-injury in infancy." (PMID 37760001, 2023).
Hyperoxaluria (1 paper, 2023). Increased excretion of oxalates in the urine. "Detection of the same genetic variant in HPRT1 and AGXT gene in two fetuses as observed in index cases with Lesch nehan syndrome and hyperoxaluria respectively helped in appropriate counselling and termination of pregnancy." (PMID 37464296, 2023).
keratitis (1 paper, 2010). A corneal disease that is characterized by inflammation of the cornea. "Namely, geNorm proposed PPIA and HRPT1 and PPIA and RPL5 pairs for chemical burn-induced CorNV in Balb/c and C57BL/6 mice, respectively, while UBC and HPRT1 and UBC and LDHA were best for Candida and Aspergillus induced keratitis in Balb/c mice, respectively." (PMID 20596249, 2010).